KRAS (KRas proto-oncogene, GTPase)
Diseases named in the same sentence as KRAS in open-access papers (continued):
Sharing a sentence is not in itself a finding about the gene and the disease.
pancreatic cancer (continued). "Solid tumors such as colorectal and pancreatic cancers showed frequent KRAS mutations, whereas some hematologic cancers such as acute lymphoblastic leukemia predominately showed NRAS mutations." (PMID 27634910, 2016). "Nearly all pancreatic cancer involves malignant transformation of pancreatic epithelial duct cells, and mutations in the KRAS oncogene are present in over 90% of metastatic pancreatic cancers." (PMID 27265611, 2016). "KRAS mutations are found in more than 90% of pancreatic cancers, and despite its frequency and being the earliest genetic alteration, previous attempts to selectively target KRAS have failed." (PMID 27244881, 2016). "KRAS mutation is often present in many hard-to-treat tumors such as colon and pancreatic cancer and it is tightly linked to serious alterations in the normal cell metabolism and clinical resistance to chemotherapy." (PMID 27323830, 2016). "In pancreatic cancer, colon cancer, and non-small cell lung cancer, the KRAS mutation rates are 90%, 45%, and 35%, respectively." (PMID 27322423, 2016). "Point mutation of the oncogene KRAS is seen in almost all early pancreatic cancer precursor lesions and in PDACs." (PMID 27267993, 2016). "In pancreatic cancer, recent meta-analysis demonstrated that KRAS mutation was a potential poor prognostic marker." (PMID 27517148, 2016). "Of the 397 patients with pancreatic cancer, 75 (18.9%) carried at least one cfDNA KRAS mutation at PDAC hotspot codons, a sensitivity close to that reported for the pilot series (17.5%)." (PMID 27705932, 2016). "In fact, most patients with pancreatic cancer carry mutational activation of the KRAS oncogene which partially accounts for a dramatically activated ERK pathway, overexpression of MMPs, and obvious invasive potential." (PMID 26649143, 2016). "We will summarize the state-of-the-art for each direction, focusing on efforts directed toward the development of therapeutics for pancreatic cancer patients with mutated KRAS." (PMID 27096871, 2016). "Some experiments have shown that farnesyltransferase inhibitor drugs, which prevent the post-translation processing of KRAS, essential for its appropriate cell-membrane localization, sensitize KRAS-mutated pancreatic cancer cells to radiation." (PMID 26884312, 2016). "KRAS (G12D mutation) has an important role in regulating pancreatic tumor metabolism via stimulation of glucose uptake and activation of the hexosamine biosynthesis and pentose phosphate pathways." (PMID 27924922, 2016). "Increased RAS pathway signaling by oncogenic KRAS mutations has been implicated as a driver in PDAC; mutations in KRAS are found in over 90% of pancreatic tumors." (PMID 26934555, 2016). "KRAS mutation is the initiating genetic event for PDAC, with KRAS mutations found in ~95% of pancreatic intraepithelial neoplasias (PanINs), the earliest pre-neoplastic stages of pancreatic cancer progression." (PMID 27096871, 2016). "A important feature of this cancer is that most pancreatic cancer cells harbor oncogenic mutations in the KRAS gene in the early stage, and the mutant KRAS is required to initiate pancreatic carcinoma." (PMID 27322423, 2016). "Allelic fractions correlated significantly with status, pancreatic cancer cases carrying cfDNA KRAS mutations at higher allelic fractions than patients with chronic pancreatitis (t-test on log10(allelic fractions) p=0.0259) and healthy controls (p=0.0008)." (PMID 27705932, 2016). "The microarray results showed that the lncRNA-NUTF2P3-001 was one of the significantly increased lncRNAs, which was positively associated with KRAS mRNA expression both in pancreatic cancer and chronic pancreatitis samples." (PMID 26755660, 2016).
pancreatic cancer (continued). "Mutations of KRAS observed in pancreatic cancers often occur in codons 12, 13, and 61, at most are G12D or G12R substitutions, which attenuates the intrinsic GTPase activity, thus, such mutations result in prolonged activation of RAS." (PMID 25699241, 2015). "Supporting measurements are provided from the LODERTM system, releasing siRNA against mutated KRAS over months in pancreatic cancer in-vivo models." (PMID 26416413, 2015). "Proportionally pancreatic tumors had the largest number of mutations detected (100% overall, 100% somatic, 85% potentially actionable, noting that KRAS was designated potentially actionable in this analysis)." (PMID 26015395, 2015). "In a recent analysis of 2,400 pancreatic cancer patients of whom 82% were found to have mutated KRAS, mutations in BRAF, EGFR, HER2, FLT3, HRAS, PDGFRA, and PTEN were identified exclusively in KRAS wild-type patients, and even there, only rarely (8%)." (PMID 26161408, 2015). "Given the almost ubiquitous occurrence of K-ras mutations and its critical role in the development of pancreatic cancer, the ideal therapeutic strategy would be the direct blocking of KRAS oncogenic signaling." (PMID 25963558, 2015). "The main objective of this study was to explore cell-autonomous vulnerabilities of pancreatic cancer cells with KRAS mutations and identify treatments that kill these cells rather than stop or slow down their growth." (PMID 26158412, 2015). "The remaining gene in our top 10 list encodes an miRNA (MIR96) known to suppress KRAS and function as a tumor suppressor in pancreatic cancer." (PMID 26039411, 2015). "An obvious example is that whilst pancreatic cancers invariably have KRAS mutation in over 90% of these cancers and a higher incidence of DPC4 inactivation of up to 55%, this is not seen to the same degree in ampullary or biliary cancers." (PMID 25890023, 2015). "This occurs primarily through the formation of DNA adducts resulting in mutations in a number of vital genes implicated in tumorigenesis, including KRAS, which is mutated in nearly all pancreatic cancers." (PMID 26264026, 2015). "Mutated KRAS was proposed to be a hallmark of pancreatic cancer since this protein is mutated in more than 90% of PDACs." (PMID 26009994, 2015). "A phase I study evaluating the activity of BEZ235 plus a MEK inhibitor (MEK162) in advanced solid tumor patients (including pancreatic cancer) with KRAS, NRAS and/or BRAF mutations has recently completed (NCT01337765)." (PMID 25935754, 2015). "We estimate that pancreatic cancer cells bearing KRAS mutation can maintain the KRAS “independent” phenotype for ≥ 30 population doublings." (PMID 26158412, 2015). "KRAS mutation (codon 12, 13, 61, or 146) was detected in 69% of the 283 patients with pancreatic cancer." (PMID 25797243, 2015). "It has been shown that these activating mutations in the KRAS are a necessary event for the initiation of pancreatic cancer and are therefore commonly found in the early precursor lesions (PanIN-1)." (PMID 25935754, 2015). "The same C118S mutation engineered into HRAS and NRAS was previously shown to reduce the tumor growth of the KRAS mutation-positive human pancreatic cancer cell line CFPac-1." (PMID 25902334, 2015). "This indicates that, for their proliferation and survival, pancreatic cancer cells are largely dependent on the activation of MAPK induced as a consequence of the synergistic effect of mutations in KRAS and an abrogation of DUSP6." (PMID 25699241, 2015). "Unfortunately, the use of targeted therapies for the treatment of pancreatic cancer has been limited secondary to the abundance of KRAS mutations." (PMID 26436951, 2015).
pancreatic cancer (continued). "To clarify the effects of adding erlotinib to gemcitabine and the roles of EGFR and KRAS mutations as predictive biomarkers in patients with advanced pancreatic cancer who receive these regimens, we performed this open-label, randomized, prospective study." (PMID 26046796, 2015). "The 3 human RAS genes (HRAS, KRAS, and NRAS) are among the most prevalent drivers of human cancer, with KRAS being mutated in 20-25% of all human tumors and up to 90% in certain cancer types, e.g. pancreatic cancer." (PMID 26028667, 2015). "A second recently published study using Guardant360 also in advanced pancreatic carcinoma found mutations detected in plasma in 84% of patients and 100% concordance with tissue analyzed for mutations in the KRAS gene." (PMID 26474073, 2015). "The expression of HER family members and NRG1β1-induced proliferation was assessed in five pancreatic cancer cell lines that harbor KRAS mutations and in one cell line (BxPC-3) wild type." (PMID 25216528, 2014). "RAGE-deficient mice have impaired oncogenic KRAS-driven pancreatic tumor growth with significant downregulation of the HIF1α signaling pathway." (PMID 25341034, 2014). "In our series, the proportion of tested patients with pancreatic cancer with KRAS mutation was similar to that reported in the COSMIC database." (PMID 25313136, 2014). "Why is KRAS preferentially mutated in pancreatic cancer and why does this member of Ras have the highest overall mutagenic propensities relative to the other two, closely related Ras members, HRAS and NRAS?" (PMID 25265995, 2014). "Activating KRAS mutation almost always drives pancreatic tumour initiation, however, deregulation of other potentially druggable pathways promotes tumour progression." (PMID 24717934, 2014). "KRAS mutation, as a popular phenomenon in pancreatic cancer patients, has been applied mostly the establishment of animal model." (PMID 24587996, 2014). "Many studies have focused on point mutations causing the constitutive activation of the oncogene KRAS which, in turn, activates mechanisms bringing pancreatic cancer onset." (PMID 24878567, 2014). "KRAS mutations are one of the earliest genetic abnormalities in the progression model for pancreatic cancer." (PMID 24783207, 2014). "In solid tumors, including colorectal, lung and pancreatic cancer, KRAS is mutated much more frequently than NRAS; the reverse is true in some hematologic cancers such as acute lymphoblastic and chronic myelomonocytic leukemias, and Hodgkin lymphoma." (PMID 25361007, 2014). "Pancreatic cancer, is characterized by near-universal mutations in the KRAS oncogene and a hypoxic and pro-inflammatory tumor microenvironment." (PMID 25341034, 2014). "In particular, KRAS is one of the most frequently mutated oncogenes across cancer types: KRAS mutations occur in approximately 60–70% of pancreatic cancers, 30% of colorectal and biliary cancers, and 20% of lung and ovarian cancers." (PMID 25093678, 2014). "Given the relatively high frequency (∼90%) of KRAS mutation in pancreatic cancer, we chose CAPAN-2 and HPAC tumor xenografts harboring distinct mutations in KRAS, namely G12D and G12V, respectively for the combination studies." (PMID 24978597, 2014). "HPDE was expected to show the “pure” phenotype of mutated GNAS, whereas the pancreatic cancer cells were expected to manifest the phenotype of mutated GNAS plus mutated KRAS (the latter corresponds to common mutations found in IPMN)." (PMID 24498386, 2014). "KRAS mutations are particularly associated with the most lethal malignancies: lung, colon and pancreatic cancer." (PMID 24583697, 2014).
pancreatic cancer (continued). "Despite KRAS being the most frequently mutated oncogene in pancreatic cancer with a reported frequency ranging between 20 and 100%, it has not been so far utilized in categorization of tumors for clinical purposes." (PMID 23565280, 2013). "There is a close association of differential RBM5 and KRAS with poor clinicopathological features, suggesting their potential roles in the progression and metastasis of pancreatic cancer." (PMID 23425895, 2013). "These mutations, especially in KRAS, are present at even higher rates in pancreatic cancer and colorectal cancer." (PMID 23991070, 2013). "In this study, we observed that KRAS mutation frequency in pancreatic tumors was consistent with ours and other previous European studies that were based on 70–100 tumors and reported a mutation frequency of 72–83%." (PMID 23565280, 2013). "Mutations of the KRAS oncogene occur frequently in pancreatic cancer and represent an attractive target." (PMID 24130864, 2013). "Another, in various cancer types well established, cause of resistance to anti-EGFR treatment is KRAS mutation, predominantly present in pancreatic cancer cells, which accounts for constitutive signaling directly downstream of EGFR." (PMID 22367239, 2013). "KRAS mutations in pancreatic cancer are believed to be the early events in neoplastic transformation." (PMID 23565280, 2013). "In order to address the issue of frequency of KRAS mutation in pancreatic cancer and impact of those mutations on disease outcome, we have in this study included a series of fully characterized 171 pancreatic tumors with complete patient data." (PMID 23565280, 2013). "We have decided to extend our observations regarding the interest of the combined treatment in pancreatic cancer by examining the efficiency of such combined treatment on two human pancreas cell lines with reported KRAS mutations." (PMID 24040391, 2013). "Taken together, our findings are consistent with RAF kinase fusions occurring in a small subset of pancreatic cancers, where they possibly substitute for KRAS mutations." (PMID 23637631, 2013). "More than 90% of pancreatic cancers harbor activating mutations of KRAS, and a subset also exhibits KRAS amplification." (PMID 23637631, 2013). "In contrast, in pancreatic cancer, which has the highest incidence of KRAS mutations of any cancer, 2 small studies showed evidence that patients with G12V (GTT) mutations have longer median survival and those with G12D (GAT) have shorter." (PMID 24066160, 2013). "More specifically, in pancreatic cancer, the most commonly reported KRAS mutation is the substitution of valine (V) or aspartic acid (D) for glycine (G) at position 2 in codon 12 (GGT [encoding G] → GTT [encoding V] or GAT [encoding D])." (PMID 24194913, 2013). "The high frequency of KRAS mutations in pancreatic cancers has been proposed as a diagnostic tumor marker, as well as a prognostic indicator." (PMID 23425895, 2013). "A study reported that gastric-type IPMNs showed a significantly higher incidence of KRAS mutations than their intestinal-type counterparts, indicating an association with the development of conventional pancreatic cancer." (PMID 24008495, 2013). "The loss of miR-145 (miR-143/145 cluster) is observed in KRAS mutated pancreatic cancers, and therapeutic restoration of these miRNAs abrogates tumorigenesis." (PMID 24040120, 2013). "Our data in this study showed that presence of any KRAS mutation in pancreatic tumors was associated with reduced survival time." (PMID 23565280, 2013). "Mutant KRAS has been extensively investigated as a marker of pancreatic cancer because mutations are basically entirely limited to one codon, and can be readily detected using molecular assays." (PMID 24084722, 2013).
pancreatic cancer (continued). "Mutation of a KRAS gene is an essential step in the development of a number of cancers, including pancreatic cancer." (PMID 23425895, 2013). "Pancreatic cancer is characterized by near-universal mutations in KRAS and frequent deregulation of crucial embryonic signaling pathways, such as the Hedgehog and Wnt-β-catenin pathways." (PMID 24231729, 2013). "The differentially expressed RBM5 and KRAS in pancreatic cancer and their significant associations with postoperative recurrence of pancreatic cancer suggests their potential use as predictors of clinical implication." (PMID 23425895, 2013). "Because of the high frequency of KRAS mutations in pancreatic cancer, KRAS has been directly targeted in pre-clinical and clinical trials, but results have been disappointing." (PMID 24130864, 2013). "The exceptions seem to be under reporting of BRAF and KRAS mutations in melanomas and pancreatic cancers respectively (10% and 20% in this study vs. 43% and 58% respectively reported in COSMIC)." (PMID 23991070, 2013). "The presence of a KRAS mutation is seen in 30% of premalignant lesions and in up to 90% of pancreatic cancer tumor specimens, suggesting that the KRAS mutation is the predominant known feature of pancreatic cancer molecular pathogenesis." (PMID 24130864, 2013). "Though, some previous reports have suggested association of KRAS mutations in resected pancreatic cancers with prognosis." (PMID 23565280, 2013). "More recently, KRAS has also been associated with the undifferentiated state of pancreatic cancer stem cells and in testicular germ cell tumors." (PMID 22737227, 2012). "More than 80∼90% of pancreatic cancers harbor mutations in codon 12 of KRAS resulting in constitutive activation of the K-RAS/B-RAF/MAPK signaling pathway." (PMID 23251334, 2012). "KRAS mutations are early events in pancreatic cancer, thus the mutations are thought to exist in all malignant cells." (PMID 23049875, 2012). "Mutations of KRAS gene are present in 75-90% of pancreatic cancers and appear to play a role in the early stages of carcinogenesis." (PMID 22458520, 2012). "Several research groups have suggested that the presence of KRAS gene mutations in tissue obtained by EUS-FNA improved the accuracy of the diagnosis of pancreatic cancer." (PMID 23197977, 2012). "In the pancreatic cancer cases studied, 88.9% (48/54; 95% confidence interval [CI]: 80.5%–97.2%) had KRAS gene mutations (codons 12 and 13), whereas 61.1% (33/54; 95% CI: 48.1%–74.1%) were unequivocally diagnosed by histocytopathology." (PMID 23197977, 2012). "Since KRAS is frequently mutated in pancreatic cancer, inhibitors of RAS and associated signaling pathways are being investigated for treatment purposes." (PMID 24213498, 2012). "KRAS mutations have been found in 65–100% of pancreatic carcinomas, 36% of CRCs and 20% of non-small cell lung cancers." (PMID 23226727, 2012). "In one study, it was shown that both primary pancreatic carcinoma and its corresponding metastasis carry the same KRAS mutation." (PMID 23119210, 2012). "TOV-942GT harboured an amplification of the KRAS locus, and while pancreatic carcinomas have been shown to have a high KRAS mutation rate, the pathology review excluded the possibility of metastasis in this case." (PMID 22163003, 2011). "In the case of pancreatic cancer, more than 90% of pancreatic adenocarcinomas show mutations in the KRAS gene which result in constitutively active Ras, which can affect the activation of the ERK MAPK pathway." (PMID 20858281, 2010). "Transition mutations of KRAS exon 2 codons 12 and 13 occur in the majority (71.4%) of pancreatic carcinoma." (PMID 21197450, 2010). "The KRAS G12 missense mutation is a major driver of pancreatic tumor development." (PMID 40906088, 2025).